MRRF (mitochondrial ribosome recycling factor)
Description:
Responsible for the disassembly of ribosomes from messenger RNA at the termination of mitochondrial protein biosynthesis. Acts in collaboration with GFM2. Promotes mitochondrial ribosome recycling by dissolution of intersubunit contacts.
Synonyms: RRF; mtRRF; MRFF
Tractability: Small molecule: a structure with a bound ligand is known. PROTAC: its protein half-life has been measured.
Gene: Protein-coding gene on chromosome 9 (122,264,603 to 122,331,337, forward strand). Ensembl gene ENSG00000148187.
Subcellular location: Mitochondrion
Subcellular location (Human Protein Atlas): Cytokinetic bridge; Microtubules
Pathways (Reactome):
Metabolism of proteins: Mitochondrial translation termination
Gene Ontology:
Molecular function: protein binding; ribosomal large subunit binding
Biological process: ribosome disassembly; translation
Cellular component: mitochondrion; mitochondrial matrix
Genetic constraint (gnomAD): Loss-of-function variants: 15 observed, 20.74 expected, observed/expected ratio (o/e) 0.72, 90% interval 0.48 to 1.11. The upper end of that interval is the gene's LOEUF score, 1.11, which puts it in group 4 of 6, group 1 being the genes least tolerant of losing a copy. Missense variants: 293 observed, 309.79 expected, observed/expected ratio (o/e) 0.95, 90% interval 0.86 to 1.04. Synonymous variants: 107 observed, 110.89 expected, observed/expected ratio (o/e) 0.96, 90% interval 0.82 to 1.13.
Homologues: Orthologues: chimpanzee MRRF (99% identical), macaque MRRF (96% identical), rabbit MRRF (88% identical), pig MRRF (87% identical), guinea pig MRRF (86% identical), mouse Mrrf (85% identical), rat Mrrf (85% identical), dog MRRF (80% identical), tropical clawed frog mrrf (57% identical), zebrafish mrrf (56% identical), Drosophila melanogaster mRRF1 (35% identical), Caenorhabditis elegans mrrf-1 (22% identical).
Diseases named in the same sentence as MRRF in open-access papers:
MRRF is named in the same sentence as 3 diseases in open-access papers, as found by Europe PMC text mining. Sharing a sentence is not in itself a finding about the gene and the disease. The quoted sentences say what the papers report.
lung carcinoma (1 paper, 2023). "Indeed, RT–PCR results indicated that the deletion of MEN1 in lung cancer cells increased the instances of short splicing isoforms in the FAM189B, NUBP2, ENDOV and TARBP2 genes, but inhibited generation of the CPSF7, MRRF and LETMD1 splicing isoforms." (PMID 37395406, 2023).
Parkinson disease (1 paper, 2020). A progressive degenerative disorder of the central nervous system characterized by loss of dopamine producing neurons in the substantia nigra and the presence of Lewy bodies in the substantia nigra and locus coeruleus. "Another group of authors obtained data on two new protein biomarkers of Parkinson’s disease—mitochondrial ribosome recycling factor (MRRF) and ribosomal protein S18 (RPS18), the increase of which is particularly relevant in determining the prodromal stage of Parkinson’s disease." (PMID 32466249, 2020).
Sepsis (1 paper, 2021). Sepsis is defined as life-threatening organ dysfunction caused by a dysregulated host response to infection. "In particular, the qPCR analysis showed significant down-regulation of RPL11, RPS21, NCBP2, and MRRF during sepsis." (PMID 34594344, 2021). "The transcription levels of RPL11 (ribosomal protein L11), RPS21 (ribosomal protein S21), NCBP2 (nuclear cap binding protein subunit 2), and MRRF (mitochondrial ribosome recycling factor) were found to be significantly reduced in the sepsis group as compared to the control group (p‐value < 0.05)." (PMID 34594344, 2021).